PCDHGB4 (protocadherin gamma subfamily B, 4)
Description:
Potential calcium-dependent cell-adhesion protein. May be involved in the establishment and maintenance of specific neuronal connections in the brain.
Synonyms: PCDH-gamma-B4; CDH20; FIB2
Tractability: Antibody: UniProt places it where antibodies can reach, with medium confidence; UniProt predicts a signal peptide or a membrane-spanning region; its Gene Ontology location is reachable by antibodies, with medium confidence; the Human Protein Atlas places it where antibodies can reach.
Gene: Protein-coding gene on chromosome 5 (141,387,698 to 141,512,975, forward strand). Ensembl gene ENSG00000253953.
Subcellular location: Cell membrane
Subcellular location (Human Protein Atlas): Nucleoplasm; Plasma membrane; Cytosol; Vesicles
Gene Ontology:
Molecular function: cell adhesion molecule binding; calcium ion binding
Biological process: calcium-dependent cell-cell adhesion; cell adhesion; homophilic cell-cell adhesion
Cellular component: membrane; plasma membrane
Genetic constraint (gnomAD): Loss-of-function variants: 36 observed, 56.93 expected, observed/expected ratio (o/e) 0.63, 90% interval 0.48 to 0.83. The upper end of that interval is the gene's LOEUF score, 0.83, which puts it in group 3 of 6, group 1 being the genes least tolerant of losing a copy. Missense variants: 1,036 observed, 1,106.4 expected, observed/expected ratio (o/e) 0.94, 90% interval 0.89 to 0.99. Synonymous variants: 418 observed, 461.82 expected, observed/expected ratio (o/e) 0.91, 90% interval 0.83 to 0.98.
Homologues: Orthologues: mouse Pcdhgb4 (84% identical), rabbit PCDHGB4 (64% identical), tropical clawed frog pcdhgb5 (38% identical). Paralogues in human: PCDHGB5 (85% identical), PCDHGB1 (72% identical), PCDHGB6 (71% identical), PCDHGB2 (70% identical), PCDHGB7 (70% identical), PCDHGB3 (69% identical), PCDHGA6 (52% identical), PCDHGA12 (52% identical), PCDHGA5 (52% identical), PCDHGA11 (51% identical), PCDHGA7 (51% identical), PCDHGA9 (51% identical), and 49 more.
Diseases named in the same sentence as PCDHGB4 in open-access papers:
PCDHGB4 is named in the same sentence as 9 diseases in open-access papers, as found by Europe PMC text mining. Sharing a sentence is not in itself a finding about the gene and the disease. The quoted sentences say what the papers report.
coeliac disease (1 paper, 2025). "One noticeable intersection among the lists is the PCDHGB4 (Protocadherin Gamma Subfamily B4), shared between type 1 diabetes (T1D), systemic lupus erythematosus (SLE) and coeliac disease (CE)." (PMID 39897058, 2025).
colorectal cancer (1 paper, 2023). A primary or metastatic malignant neoplasm that affects the colon or rectum. "Among the mutated genes in the adenomatous tissue samples involved in our study, PCDHGB4, AHRR, KIF4, LPAR6, NBPF1, and NCEH1 were already associated with colorectal cancer formation, while ANKRD30A, ITIH1, and KIAA0556 were related to other types of cancers." (PMID 36765865, 2023).
endometrial cancer (1 paper, 2022). Primary or metastatic malignant neoplasm involving the endometrium (mucous membrane that lines the endometrial cavity). "PCDHGB4 is also a protein coding gene that is identified as a potential passenger gene in a study related to endometrial cancer, and novel mutations of the gene are only found in tumor samples." (PMID 35428183, 2022).
tumor (4 papers, 2009 to 2025). "It was further found that PCDHGB4 played an important role in tumor immunity and confirmed that PCDHGB4 was associated with immune checkpoints, immune regulatory genes, and methyltransferases." (PMID 38590195, 2024). "PCDHGB4 was related to the poor prognosis of patients, and PCDHGB4 was closely related to the infiltration and pathway of tumor immune cells." (PMID 38590195, 2024). "Analysis of PCDH methylation in microdissected perilobar nephrogenic rests, presumptive WT precursor lesions, revealed no PCDH hypermethylation but hypermethylation was evident at the PCDHGA3 and PCDHGB4 genes in a set of stromal-predominant tumours." (PMID 19956686, 2009). "These include PCDHGA3, hypermethylated in 24/27 tumours (89%), PCDHGB4 (23/25, 92%), PCDHGA2 (11/13, 85%) and PCDHB3 (21/33, 64%)." (PMID 19956686, 2009). "We found that the expression of 9 DE-ceRNAs were significantly different between tumor tissues and normal tissues, including the upregulated H19, HOTAIR, miR222, miR148a, PCDHGB4, GMNC and HMGA2 and the downregulated LRP2 and MBP in tumors." (PMID 40351420, 2025).
PCDHGB4 also shares sentences with these, for which no sentence is quoted: cancer (2 papers); adenoma (1); Lung Squamous Cell Carcinoma (1); systemic lupus erythematosus (1); type 1 diabetes (1).